MRPS16 (mitochondrial ribosomal protein S16)
Synonyms: MRP-S16; S16mt; RPMS16; CGI-132; bS16m; COXPD2
Tractability: Small molecule: a structure with a bound ligand is known. PROTAC: ubiquitination databases record sites on it; its protein half-life has been measured.
Gene: Protein-coding gene on chromosome 10 (73,248,843 to 73,252,693, reverse strand). Ensembl gene ENSG00000182180.
Subcellular location: Mitochondrion
Subcellular location (Human Protein Atlas): Mitochondria; Cytosol
Pathways (Reactome):
Metabolism of proteins: Mitochondrial ribosome-associated quality control; Mitochondrial translation elongation; Mitochondrial translation initiation; Mitochondrial translation termination
Gene Ontology:
Molecular function: protein binding; structural constituent of ribosome
Biological process: mitochondrial translation; translation
Cellular component: mitochondrial small ribosomal subunit; mitochondrion; mitochondrial inner membrane; ribosome
Genetic constraint (gnomAD): Loss-of-function variants: 5 observed, 11.32 expected, observed/expected ratio (o/e) 0.44, 90% interval 0.23 to 0.93. The upper end of that interval is the gene's LOEUF score, 0.93, which puts it in group 3 of 6, group 1 being the genes least tolerant of losing a copy. Missense variants: 179 observed, 185.32 expected, observed/expected ratio (o/e) 0.97, 90% interval 0.85 to 1.09. Synonymous variants: 76 observed, 69.32 expected, observed/expected ratio (o/e) 1.1, 90% interval 0.91 to 1.33.
Gene-disease validity (ClinGen):
ClinGen rates the evidence that MRPS16 causes each of these diseases.
mitochondrial disease (autosomal recessive): Limited.
Homologues: Orthologues: chimpanzee MRPS16 (100% identical), macaque MRPS16 (93% identical), guinea pig MRPS16 (90% identical), mouse Mrps16 (90% identical), rat Mrps16 (88% identical), zebrafish mrps16 (60% identical), tropical clawed frog mrps16 (58% identical), Caenorhabditis elegans mrps-16 (41% identical), Drosophila melanogaster mRpS16 (40% identical).
Diseases named in the same sentence as MRPS16 in open-access papers:
MRPS16 is named in the same sentence as 10 diseases in open-access papers, as found by Europe PMC text mining. Sharing a sentence is not in itself a finding about the gene and the disease. The quoted sentences say what the papers report.
glioma (7 papers, 2020 to 2026). A benign or malignant brain and spinal cord tumor that arises from glial cells (astrocytes, oligodendrocytes, ependymal cells). "By RT‐PCR, cell counting, flow cytometry, MTT assays, colony formation and injection of mice, we deeply explored the role of MRPS16 in glioma cell growth and the underlying mechanism." (PMID 41578162, 2026). "However, the role of MRPS16 in glioma cell proliferation, which is closely associated with tumour malignancy, remains unclear." (PMID 41578162, 2026). "The Wnt/β—Catenin/NFATC2 pathway plays a role in promoting glioma cell proliferation by MRPS16, which is shown in our experimental data." (PMID 41578162, 2026). "Through further prediction and gene transformation of cultured cells, it is confirmed that the presence of MRPS16 promotes the proliferation of glioma cells through the Wnt/β‐catenin/NFATC2 pathway." (PMID 41578162, 2026). "Here we validate that MRPS16 does exert regulatory influence over glioma cells, and it is an extensive promotion of proliferation in glioma cells." (PMID 41578162, 2026). "Then we searched for ways MRPS16 helps glioma cells replicate and we wanted to know the exact genes or proteins controlling that." (PMID 41578162, 2026). "In the current study, it was found that MRPS16 shows notably high expression within human glioma tissue samples." (PMID 41578162, 2026). "In the cultured glioma cells, glioma cell proliferation was inhibited, and cell cycle arrest and cell apoptosis were induced after MRPS16 knockdown." (PMID 41578162, 2026). "In the report on MRPS16 and glioma cell progression, MRPS16 was shown to facilitate glioma cell progression via the PI3K/AKT/Snail signalling axis." (PMID 41578162, 2026). "Inhibition of glioma growth and proliferation was largely achieved via promotion of cell cycle stoppage, inducing apoptosis by means of silencing the MRPS16 expression level." (PMID 41578162, 2026). "By comparison, we have made it clear that MRPS16 regulates the proliferation of glioma cells through the increased expression of NFATC2." (PMID 41578162, 2026). "To assess the effects of MRPS16 knockdown on glioma cell proliferation in vivo, we intraperitoneally injected the MRPS16 knockdown glioma U87 cells into the BALB/c mice and then kept them for a period of 6 weeks." (PMID 41578162, 2026). "Knockdown of MRPS16 can slow down the growing speed of glioma cells (such as U87 or U251 Cells), help them die." (PMID 41578162, 2026). "And it is also put forth that NFATC2 takes part in regulating the growth of glioma cells by way of MRPS16, Statistical significance was assessed using Student's t‐test." (PMID 41578162, 2026). "In BALB/c mice inoculated with glioma cells knocked down for MRPS16, it was found that tumour proliferation and growth were relatively slower than the control." (PMID 41578162, 2026). "High expression of MRPS16 was displayed in human glioma, and it was connected with the poor prognosis of glioma." (PMID 41578162, 2026). "In glioma cells, we see an increase in the amount of cell death upon the reduction in expression of MRPS16." (PMID 41578162, 2026). "Through Western blot, qRT-PCR, and IHC analyses, researchers have found that MRPS16 expression is significantly increased in tumor tissues compared to normal brain tissues, especially in high-grade gliomas." (PMID 40371222, 2025). "Wang et al15 reported that MRPS16‐OE improves glioma progression through PI3K/AKT signalling activation." (PMID 38506080, 2024). "The activation of the PI3K/AKT signaling pathway by MRPS16 leads to elevated levels of Snail protein expression, thereby promoting glioma progression." (PMID 37660060, 2023). "In an in vitro study, MRPS16 inactivation was found to suppress tumor cell growth, migration, and the invasion of human glioma cells by inhibiting the PI3K/AKT signaling." (PMID 34361072, 2021). "The overexpression of MRPS16 is often found in glioma tissues and promotes tumorigenesis in animal models." (PMID 34361072, 2021).
glioma (continued). "We found that MRPS16 was often up-regulated in glioma tissues, and MRPS16 knockdown obviously suppressed tumor cell growth." (PMID 32127931, 2020). "According to our data and previous reports, we determined a model for how MRPS16 promotes glioma progression." (PMID 32127931, 2020). "According to our study, we verified that over-expression of MRPS16 promoted tumor cell growth, migration and invasion, which indicates that MRPS16 has strong tumorigenicity in glioma." (PMID 32127931, 2020). "Then, we analyzed the correlation between MRPS16 mRNA expression levels and clinicopathological characteristics in 61 glioma samples." (PMID 32127931, 2020). "The molecular effects of MRPS16 in glioma cells were tested by Western blotting, quantitative polymerase chain reaction (qRT-PCR), EdU, CCK-8, colony formation, Transwell migration and invasion assays." (PMID 32127931, 2020). "The results demonstrated that MRPS16 protein and mRNA expression levels were up in the glioma cell line compared with the human brain gliocyte cell line." (PMID 32127931, 2020). "Knockdown of MRPS16 might make for more comprehensive apoptosis of glioma cells; that is to say, it could increase inhibition by way of regulating cell multiplication." (PMID 41578162, 2026). "MRPS16 was reported to promote tumour progression by the PI3K/AKT/Snail pathway in glioma." (PMID 41578162, 2026). "The inhibition of proliferation of glioma cells was achieved again through the knockdown of MRPS16." (PMID 41578162, 2026). "MRPS16 can promote glioma tumour proliferation and inhibit glioma cell apoptosis, so it might be supposed that MRPS16 could control the multiplication of glioma cells by way of the way in which Wnt/β—Catenin/NFATC2." (PMID 41578162, 2026). "So, MRPS16 has a considerable positive correlation with the development of glioma cells, which means it may be worth looking at closely for targeted treatments." (PMID 41578162, 2026). "MRPS16 expression was significantly higher in glioma tissues compared with normal brain tissues." (PMID 41578162, 2026). "In conclusion, our results showed that MRPS16 is a novel oncogene related to glioma proliferation." (PMID 41578162, 2026). "From our study we found out that MRPS16 showed strong upregulation in the samples of glioma tissue." (PMID 41578162, 2026). "The differential expression of MRPS16 in glioma vs. normal brain tissue seems to be quite obvious." (PMID 41578162, 2026). "In order to inhibit GDN4 and thus target glioma, the targeting of MRPS16 might be a new approach to treat glioma." (PMID 41578162, 2026). "Furthermore, the Kaplan-Meier analysis indicated that MRPS16 mRNA expression levels were significantly associated with poorer disease-free survival (DFS) and overall survival (OS) in glioma patients." (PMID 32127931, 2020). "In addition, subsequent mechanistic studies indicated that MRPS16 promoted glioma cell growth, migration and invasion by the activating PI3K/AKT/Snail axis." (PMID 32127931, 2020). "In conclusion, we propose and clarify that MRPS16 promotes glioma progression through the PI3K/AKT/Snail signaling axis and that these molecules may be potential new targets for the treatment of glioma." (PMID 32127931, 2020). "Herein, we found the oncogenicity of MRPS16 in the development of glioma." (PMID 32127931, 2020). "Currently, accumulating evidence has focused on the function of MRPS16 proteins in mitochondrial translation defects; however, their function in glioma remains unknown." (PMID 32127931, 2020). "To verify whether Snail is involved in MRPS16-regulated glioma cell growth, migration and invasion, we over-expressed Snail in tumor cells." (PMID 32127931, 2020). "Hence, based on findings of this research, we report that MRPS16 promoted glioma progression via the PI3K/AKT/Snail axis." (PMID 32127931, 2020). "Here, we report the clinical relevance and function of MRPS16 in glioma." (PMID 32127931, 2020).
glioma (continued). "Glioma cells proliferating induced by MRPS16 may involve Wnt/β − Catenin/NFATC2 signaling pathway." (PMID 41578162, 2026). "Furthermore, it is also possible that the effect of Wnt/β—Catenin/NFATC2 signalling pathway on glioma cell proliferation may occur through MRPS16." (PMID 41578162, 2026). "Inhibition of MRPS16 may be a promising and effective treatment option for gliomas." (PMID 41578162, 2026). "Additionally, silencing MRPS16 significantly reduces the expression levels of proteins such as Snail, p-AKT, and p-PI3K in U-138MG and U-87MG cells, further indicating that MRPS16 promotes glioma cell proliferation and invasion through the PI3K/AKT/Snail signaling axis." (PMID 40371222, 2025). "Similarly, the expression of MRPS16 in glioma has also garnered significant attention." (PMID 40371222, 2025). "Collectively, MRPS16 might enhance glioma progression via PI3K/AKT signalling activation." (PMID 38506080, 2024). "Therefore, we surmised that over-expression of MRPS16 might induce Snail expression, thus promoting glioma cell growth, migration and invasion." (PMID 32127931, 2020). "MRPS16 and NFATC2 promote glioma cell proliferation, which was confirmed by in vivo BALB/c mice inoculation." (PMID 41578162, 2026). "To verify NFATC2 as the mediator for MRPS16's regulation over glioma cell proliferation, we conducted OE experiments with regard to NFATC2 accompanied by MRPS16 knockdown." (PMID 41578162, 2026). "Our experimental data also indicated that MRPS16 activated the PI3K/AKT signaling pathway, which in turn promotes the expression levels of Snail protein, thus promoting the progression of glioma." (PMID 32127931, 2020). "Then, we performed IHC to detect MRPS16 protein expression levels in NBT and different grades of glioma tissue." (PMID 32127931, 2020). "Subsequently, we detected MRPS16 protein and mRNA expression levels in normal brain tissue (NBT) and different grades of glioma tissue." (PMID 32127931, 2020). "First, MRPS16 protein and mRNA expression levels in normal brain tissue (NBT) and different grades of glioma tissue were measured by Western blotting and qRT-PCR." (PMID 32127931, 2020). "Overall, MRPS16 and NFATC2 were shown to promote glioma cell proliferation in BABL/c mice." (PMID 41578162, 2026). "A recent study found that MRPS16 promoted the growth, migration, and invasion of glioma cells by activating PI3K/AKT nail axis, these processes can be eliminated by knocking down MRPS16 and similar trends are observable in U251 and A172 cells after deletion of MRPL42." (PMID 33238645, 2020). "MRPS16 has not been reported to be involved in glioma cell proliferation before." (PMID 41578162, 2026). "Regarding the effect of MRPS16 on glioma, no other research has mentioned this." (PMID 41578162, 2026). "The role of MRPS16 in glioma development has not yet been fully elucidated." (PMID 41578162, 2026).
ovarian carcinoma (3 papers, 2021 to 2025). A malignant neoplasm originating from the surface ovarian epithelium. "Kaplan-Meier survival analysis shows that high expression of MRPL15, MRPL36, MRPL39, and MRPS16 is significantly associated with poorer OS in ovarian cancer patients." (PMID 40371222, 2025). "(2021) examined the expression of six MRPs in a variety of ovarian cancer datasets, including TCGA, GTEx (Genotype-Expression Tissue Portal), and Oncomine, and found a strong positive correlation between increased MRPS16 and poor survival in ovarian cancer." (PMID 39354291, 2024). "MRPL10, MRPL15, MRPL36, MRPL39, and MRPS16 were highly expressed in ovarian cancer, whereas MRPS31 showed the opposite tendency." (PMID 33934540, 2021). "The expression of all six MRPs in ovarian cancer was positively correlated, with the strongest correlation being between MRPS16 and MRPL39 (r = 0.56, p < 2.2e‐16)." (PMID 33934540, 2021). "Notably, MRPS16 was upregulated in response to HE4 (human epididymis protein 4), an established ovarian cancer biomarker associated with metastasis." (PMID 39354291, 2024). "Six MRPs (MRPL10, MRPL15, MRPL36, MRPL39, MRPS16, and MRPS31) related to HE4 in ovarian cancer were selected." (PMID 33934540, 2021).
brain glioma (1 paper, 2020). A malignant glioma that involves the brain. "First, we measured MRPS16 protein and mRNA expression levels by Western blot and qRT-PCR in two human brain gliocyte cell lines (NHA and HA) and three human brain glioma cell lines (U-138MG, U-251MG and U-87MG)." (PMID 32127931, 2020).
lymph node metastasis (1 paper, 2024). "Based on univariate and multivariate Cox regression analyses, MRPS16 mRNA overexpression was correlated to TNM stage and lymph node metastasis; hence, it was an independent prognostic factor for poor survival of LAUD patients, indicating that MRPS16 might be a potential LAUD biomarker." (PMID 38506080, 2024).
cancer (7 papers, 2020 to 2026). A tumor composed of atypical neoplastic, often pleomorphic cells that invade other tissues. "In high-risk ovarian and lung cancers, the use of MRPS16 as a biomarker of cancer progression has been demonstrated." (PMID 39354291, 2024). "To clearly explain the underlying mechanism of MRPS16-mediated regulation of tumor progression, we performed the Cignal Finder Cancer 10-Pathway Reporter Kit to screen possibly involved signaling axes." (PMID 32127931, 2020). "Analysis from the TCGA database also indicated that the MRPS16 level in cancer is higher than that in control." (PMID 41578162, 2026). "Furthermore, there is compelling emerging evidence that increased MRPS12, MRPS16 and MRPS18B expression and association with metastatic capacity are observed across five different cancer types, collectively." (PMID 39354291, 2024). "Although MRPS16 is involved in cancer development, its mechanisms in developing LAUD remain unclear." (PMID 38506080, 2024). "Hence, we proved that MRPS16 contributes to cancer development." (PMID 32127931, 2020). "Based on Cignal finder cancer 10‐pathway reporter array used for screening the potentially involved signalling pathways in this process, PI3K/AKT signalling axis was significantly inhibited by MRPS16 knocking down in H23 and H2030 cells, in contrast to the other signalling axis." (PMID 38506080, 2024).